NF1 (neurofibromin 1)
Diseases named in the same sentence as NF1 in open-access papers (continued):
Sharing a sentence is not in itself a finding about the gene and the disease.
melanoma (continued). "At the molecular level, melanoma can be classified into four main types: v-Raf murine sarcoma viral oncogene homolog B (BRAF)-mutant, neuroblastoma RAS viral oncogene homology (NRAS)-mutant, neurofibromatosis type 1 (NF1)-mutant, and triple-negative or wild-type melanoma." (PMID 31684113, 2019). "Importantly, we demonstrate that USP28 expression is deleted in ∼10% of all melanoma patients, of which half of these patient’s harbor mutations in BRAF (V600E), NF1, or NRAS, supporting a role for USP28 loss in melanoma progression." (PMID 29880484, 2018). "To assess whether the loss of CAPN1 in melanoma cells could also stabilize NF1 levels and reduce melanoma cell proliferation, we used small interfering RNA (siRNA) to deplete CAPN1 in both A375 and 74T melanoma cells." (PMID 30131853, 2018). "As NF1 is a tumor suppressor gene, we were interested in investigating whether CAPN1 could degrade NF1, which would reveal a new mode of regulation of NF1 in melanoma, in addition to the degradation of NF1 by the ubiquitin-proteasome pathway." (PMID 30131853, 2018). "Both cell lines are NF1 wild-type, with A375 also containing a BRAFV600E mutation and 74T, an NRASQ61K mutation, which allowed us to screen for NF1 interactions in the two major mutational backgrounds of melanoma." (PMID 30131853, 2018). "Neurofibromin 1 (NF1), a tumor suppressor that negatively regulates RAS through its GTPase activity, is highly mutated in various types of sporadic human cancers, including melanoma." (PMID 30131853, 2018). "The fact that CAPN1 inhibition has growth inhibitory effects on NF1 wild-type and as well on NF1 mutant melanoma cell lines could have a beneficial therapeutic potential." (PMID 30131853, 2018). "Interestingly, we found that the EPE peptide was effective not only in reducing the viability of many BRAF mutant melanomas, but it also affected some cell lines bearing NRAS and/or NF1 mutations as well." (PMID 29180761, 2017). "Although NF1 is associated with pigmentary abnormalities such as CALMs, malignant melanoma is not a tumour type associated with NF1." (PMID 28637487, 2017). "Furthermore, NF1‐mutant melanomas have been found to be dependent on MAPK signaling and to respond to inhibitors targeting key players of this pathway (MEK, ERK)." (PMID 28267273, 2017). "Finally, other less frequently mutated melanoma genes (KRAS, HRAS, KIT, GNAQ, GNA11) were enriched in tumors wild‐type for BRAF, NRAS, and NF1." (PMID 28267273, 2017). "This led to their proposal that NF1 may function as a tumour suppressor gene in the development or progression of malignant melanoma." (PMID 28637487, 2017). "Somatic NF1 alterations in melanoma were discovered in the early 1990s." (PMID 28267273, 2017). "BRAF in mucosal melanoma is mutated in <10% of patients, and these mutations occur in association or not with NF1 mutations." (PMID 29156643, 2017). "The melanomas used here include BRAF-mutant cells (HT144, 451Lu and MB2309), NRAS-mutated cells (WM852c, SKMEL-30, Hs852T), NF-null cells (Hs852T), or wild-type cells for the common mutations in BRAF, NRAS, or NF1 (MB2141)." (PMID 27086916, 2017). "In this context, it is important to underline that desmoplastic melanomas and malignant peripheral nerve sheath tumor (MPNST) are the two tumors displaying the highest frequency of NF1 mutations; interestingly, these two tumors are cytologically and histologically similar." (PMID 29156643, 2017). "In addition, preclinical studies have proposed sensitivity to MEK inhibition for NF1‐impaired melanomas." (PMID 28267273, 2017).
melanoma (continued). "Interestingly, RMEL3 was significantly higher in BRAFmt melanoma compared to triplewt (RAS/BRAF/NF1) melanoma and expression levels were negatively correlated with melanoma progression." (PMID 28350340, 2017). "An increased risk of death from melanoma (five‐year disease‐specific survival, DSS; HR, 1.9; 95% CI, 1.21–3.10; P = 0.046) and poor OS (HR, 2.0; 95% CI, 1.28–2.98; P = 0.01) were observed in the NF1 subtype compared to the reference group, BRAF." (PMID 28267273, 2017). "Excitingly, these results were observed even in the melanomas that have relapsed from molecular-targeted or immune-therapies and also those with varying genetic backgrounds (wild type or mutated for BRAF, NRAS, or NF1)." (PMID 27086916, 2017). "However, Ranzani and colleagues also claim that most BRAF/NRAS wild‐type melanomas are highly sensitive to MEK inhibition irrespectively of the NF1 protein level." (PMID 28267273, 2017). "We treated NRAS-mutant (YUGASP, SKMEL-2, SKMEL-103, and M318), BRAF-mutant (SKMEL-28 and A375), NF1-mutant/null (MeWo and YUTOGS), and NRAS/BRAF/NF1 wild-type (YUVON) melanoma cells with three DNA replication stress-inducing agents: aphidicolin, camptothecin, and hydroxyurea." (PMID 27608486, 2016). "Another small molecule SBI-0640756 (SBI-756), a first-in-class inhibitor that targets EIF4G1 and disrupts the EIF4F complex, can effectively inhibit the growth of NRAS, BRAF, and NF1-mutant melanomas in vitro and delay the onset and reduce the incidence of Nras/Ink4a melanomas in vivo." (PMID 27003362, 2016). "Current evidence suggests that genomic changes in DM are very different to that of conventional melanoma, although the only well‐established defining features are a markedly reduced frequency of activating BRAF mutations and loss‐of‐function mutations in NF1." (PMID 26663830, 2016). "The same relationship likely applies to melanoma cell lines as well, since most of these tumors harbor activating mutations in the RAS-MAPK pathway, including BRAF V600E and NRAS Q61L/R, as well as the loss of NF1 in a subset of cases." (PMID 27130733, 2016). "Loss of NF1 function, a well-known tumour-suppressor gene in melanoma, has been implicated on multiple occasions in resistance to PLX4032 targeted therapies in BRAF-mutant melanoma." (PMID 25980496, 2015). "With loss of NF1 and more recently an increase of CDK2 (in association with MITF) in melanomas being involved in the resistance to BRAF-inhibitor (BRAFi) therapy, we next sought to investigate whether miR-514a might be involved in this process." (PMID 25980496, 2015). "Mutations in the NF1 cooperate with BRAF mutations in a mouse model of melanomagenesis by suppressing BRAF-induced senescence (OIS), promoting melanocyte hyperproliferation and enhancing melanoma development." (PMID 24743024, 2014). "Moreover, NF1 expression is low in 47% of uveal melanomas and allelic losses are seen in other types of melanoma." (PMID 24743024, 2014). "Some neurofibromatosis patients with inactivation of NF1 develop melanomas." (PMID 24743024, 2014). "Most melanomas that arise in the setting of NF-1 are ocular." (PMID 15363097, 2004). "It is well established that developmental programs reminiscent of embryonic NC become reactivated in melanoma, and it is conceivable that this also occurs in our MPNST model, similar to processes described in MPNSTs driven by genetic loss of NF1 and PRC2 deficiency." (PMID 41063628, 2025).
melanoma (continued). "Melanomas can be further classified into four genomic subtypes based on the presence of specific driver mutations, namely B-Raf Proto-Oncogene (BRAF)-mutant, neuroblastoma RAS viral oncogene homolog (NRAS)-mutant, neurofibromatosis type I (NF1)-loss, and triple wild-type (TWT)." (PMID 40867277, 2025). "Our analysis showed modest NF1 overexpression, suggesting that the cases analyzed may not follow the same NF1 loss pattern observed in human melanomas." (PMID 40647405, 2025). "Activation of the PI3K/AKT pathway in classical NF1 and NF1 melanoma may facilitate tumour growth." (PMID 39355740, 2024). "PD-L1 expression is independent of melanoma driver mutation status (BRAF/RAS/NF1)." (PMID 37239381, 2023). "In addition, melanoma patients were also divided into four subtypes based on some mutated genes, and they were B-Raf Proto-Oncogene, Serine/Threonine Kinase (BRAF) hotspot, RAS hotspot, Neurofibromin 1 (NF1) mutant, and Triple-WT (wild-type)." (PMID 37036471, 2023). "Additionally, the alterations in the NF1 gene are related to several human highly aggressive malignancies diseases including NF1, glioblastoma, melanoma, ovarian carcinoma, lung cancer, cholangiocarcinoma, breast cancer, lymphoblastic leukemia, and other types of tumors." (PMID 36009591, 2022). "MEK inhibitors for NF1-mutation melanoma: Although NF1-mutant melanoma patients do not usually express NRAS or BRAF mutations, inhibition of the BRAF, MEK and mTOR pathways may be therapeutic since the NF1 mutation increases RAS/MAPK pathway signalling." (PMID 36232957, 2022). "Apart from the activating NRAS mutations (linked with high NRAS expression) and the inactivating NF1 mutations (linked with decreased NF1 expression), all the other mutations were randomly distributed across all melanoma tumors, irrespective of their gene expression." (PMID 36389735, 2022). "Two of these four melanomas had mutations in NF1, one in KIT and one in GNA11 (data not shown)." (PMID 36077603, 2022). "Previous studies have demonstrated that antioncogene NF1 may be regulated by some miRNAs during the occurrence of lung squamous cell carcinoma, ovarian cancer, and melanoma, but the miRNA profile in the UPS sarcoma tissue and miRNAs, which regulate NF1 in the initiation of UPS, are still unknown." (PMID 35559021, 2022). "Interestingly, distinct hypermethylated genes have been found associated with genetic mutation subgroups, e.g., NF1 hypermethylation with NF1- and RAS-mutated melanomas, PTEN hypermethylation with BRAF-mutated, and CDK2A/B hypermethylation with BRAF-, RAS-, NF1-mutated and triple-WT melanomas." (PMID 35163453, 2022). "Noteworthy was also the observation from the 3-institution cohort that genetic aberrations of specific melanoma-associated genes were less frequent in APC/CTNNB1-mutant stage IV melanomas than the incidence of these mutations without (e.g., NF1, RAC1, and PTEN)." (PMID 34986841, 2022). "In addition, the absence of neurofibromin has been reported in primary melanomas, which led to the proposal that NF1 may function as a tumor suppressor gene and is crucial in the progression of melanoma." (PMID 34680938, 2021).
melanoma (continued). "Indeed, in melanoma other oncogenic driver mutations mediate tumorigenesis via activation of MAPK/ERK signaling, including activating NRAS mutations and loss-of function mutations in NF1, a GTPase known to downregulate RAS activity." (PMID 34025662, 2021). "Hence, we reasoned that co-inhibition of BCL2 and MCL1 in nf1/pten-mutant melanoma cells might produce an even greater synergistic antitumor effect than observed with either inhibitor given individually with sirolimus." (PMID 34331013, 2021). "Indeed, while the antitumor response of nf1/pten-mutant melanomas to the combination of sirolimus and chloroquine initially appeared promising, the treated fish died due to toxicity to normal tissues, illustrating the importance of analyzing this drug combination in an in vivo model system." (PMID 34331013, 2021). "Interestingly, 20–30% of NF1 deletions have been found in BRAF and NRAS wild type melanomas suggesting that NF1 may be implicated in MAPK pathway activation." (PMID 34680938, 2021). "However, preclinical evidence suggests that NF1 mutant melanomas are dependent on MEK signaling and may be sensitive to MEK inhibitors." (PMID 34831002, 2021). "Currently, there are no ongoing clinical trials that evaluate NF1-targeted drugs, but two experimentations regard specifically NF1-mutated melanoma patients, treated with either a MEK inhibitor plus a FAK inhibitor or with RMC-4630, a potent and selective inhibitor of SHP2." (PMID 32850962, 2020). "Melanomas with NF1 mutations may not respond to MEK inhibitors (although neurofibromatosis is responsive) because melanomas tend to have important co-alterations, whereas neurofibromatosis is driven only by NF1 alterations." (PMID 32066498, 2020). "Moreover, NF1 together with BRAF and NRAS has been found significatively mutated in melanoma." (PMID 32850962, 2020). "The Cancer Genome Atlas Network has recently provided a potential step ahead in the comprehension of melanoma genesis, proposing a classification of melanoma based on protein, RNA and DNA analysis from over 300 melanoma patients, in addition to BRAF, NRAS, and NF1 mutational profile." (PMID 33233603, 2020). "In addition to diagnostics and clinical-pathological classification into superficial spreading, nodular, lentigo maligna, and acrolentiginous melanomas, recent molecular diagnostics can delineate subtypes of melanoma (possessing mutations in BRAF, NF1, RAS, or triple wild type)." (PMID 30357519, 2019). "However, while NF1 and SPRED1 mutations typically co-occur in cutaneous melanoma, in our study of mucosal melanomas, most SPRED1 aberrations identified in WGS samples (11/13) occurred in NF1 wild-type samples, with only two SVs in SPRED1 co-occurring with NF1 mutations." (PMID 31320640, 2019). "Thus, NF1 can be qualified as a potent tumor suppressor in melanomas." (PMID 29534457, 2018). "We further classified the 89 samples into the four molecular subtypes, BRAF mutated (47% in melanoma TCGA), RAS mutated (NRAS/KRAS/HRAS mutations, 29%), NF1 mutated (9%), and Triple-WT (subgroup lacking above mutations, 15%), proposed by the recent TCGA melanoma cohort." (PMID 30373548, 2018). "However, due to emergent resistance to single-agent RAFi in patients, combination treatments of BRAFi (dabrafenib) with MEKi (trametinib) have been developed for melanomas and are also being tested in pediatric patients with plexiform NF-1, BRAF-V600E refractory/relapsed tumors (NCT02124772)." (PMID 29156677, 2017).
melanoma (continued). "Indeed, it was found that NF1 suppression led to a 31-fold increase in resistance to PLX4720, as well as a partial (7-fold) resistance to MEK inhibition, demonstrating that human melanoma samples with innate resistance to BRAF inhibition and sensitivity to a MEK inhibitor harboured NF1 mutations." (PMID 28637487, 2017). "In addition, NF1 mutations may also play role in the intrinsic and acquired resistance to RAF inhibition in melanoma." (PMID 28267273, 2017). "As the studies of the major genomic aberrations in melanoma have been extensively reviewed elsewhere, this section will describe a number of the most common driver mutations seen in cutaneous melanoma [BRAF, NRAS, NF1, microphthalmia-associated transcription factor (MITF), and PTEN]." (PMID 29276510, 2017). "Moreover, the melanoma-derived fibroblasts (CAF1-4) exhibit an activated phenotype as shown by a higher α-SMA expression compared to the fibroblasts derived from normal skin (NF1-3)." (PMID 28423623, 2017). "Also, we assessed the clinical implication of BRAF, RAS, NF1, and triple‐wild‐type melanomas." (PMID 28267273, 2017). "Furthermore, NF1-associated drug resistance to RAF and EGFR inhibitors, tamoxifen and retinoic acid, has been observed in melanoma, lung cancers, breast cancers and neuroblastoma, respectively, and melanoma cells with BRAF/NF1 mutations develop resistance to BRAF inhibitors." (PMID 28637487, 2017). "Notably, knockdown of IFI6 in BRAF-mutant, NF1-deficient, or triple wild-type melanoma did not alter the expression of E2F2 or its target genes." (PMID 27608486, 2016). "Furthermore, as miR-514a is expressed in ~70% of melanoma samples tested, we believe that miR-514a binding could be an important regulator of NF1, and as such warrants further investigation." (PMID 25980496, 2015). "More importantly, the absence of NF-1 in our patient may have implications for the potential association between malignant melanoma and NF-1." (PMID 15363097, 2004). "However, it is unclear whether patients with NF-1 have an inherently higher propensity to develop malignant melanomas than the general population." (PMID 15363097, 2004). "Additionally, melanoma is not a diagnostic criteria for NF-1, as associated lesions are required to be for the definition of segmental NF-1." (PMID 15363097, 2004). "Here, we report that the mTOR inhibitor sapanisertib improves the efficacy of combined belvarafenib and cobimetinib therapy in NRAS, NF1, and KIT-mutant melanomas." (PMID 42091854, 2026). "This splicing bias leads to preferential missplicing of NF1, a RAS inhibitor, resulting in RAS hyperactivation and accelerated melanoma progression in mouse models." (PMID 42066087, 2026). "Trametinib is an ERK/MAPK inhibitor, historically used in BRAF-mutant melanoma and NSCLC and in NF1-related nervous system tumors recently." (PMID 40052442, 2025). "Actionable gene alterations in BRAF, NRAS, NF1, and KIT are common in Japanese patients with melanoma." (PMID 39823560, 2025). "Molecular parallels between COM and human melanoma, particularly MAPK pathway alterations and genes like BRAF, NRAS, MITF, and NF1, further support this study’s relevance." (PMID 40647405, 2025). "These alterations disrupt NF1’s ability to regulate RAS signaling, contributing to melanoma progression." (PMID 40872623, 2025). "The impact of tovorafenib on tumor growth was assessed in two different NF1-LOF mutant models, including an NF1-LOF mutant ERMS PDX model and an NF1-LOF melanoma xenograft tumor model, MeWo." (PMID 40111124, 2025). "The Cancer Genome Atlas (TCGA) project (2015) classified 333 melanomas into BRAF-mutant, RAS-mutant, NF1-mutant, and Triple Wild-Type (Triple-WT) groups." (PMID 40508177, 2025). "In the TCGA cohort, the four distinct subtypes of melanoma (TCGA-SKCM), BRAF, NRAS, triple wild type, and NF1 put together, constitute only 25% of the samples, leaving ~75% with no clear mutation association." (PMID 41368197, 2025).